DLG2 (discs large MAGUK scaffold protein 2)
Diseases named in the same sentence as DLG2 in open-access papers (continued):
Sharing a sentence is not in itself a finding about the gene and the disease.
osteosarcoma (9 papers, 2019 to 2023). A usually aggressive malignant bone-forming mesenchymal neoplasm, predominantly affecting adolescents and young adults. "DLG2 (Disks Large Homolog 2) as a tumor suppressor candidate, of which its structural mutation is associated with osteosarcoma, and DLG2 deletion accelerates the growth of bone tumors in canine and human cell lines." (PMID 36980850, 2023). "This approach was successful in a mouse osteosarcoma model of DLG2 loss." (PMID 30890123, 2019). "Among them, CTNNA3 was reported as a tumor suppressor in HCC before and the same as DLG2 in osteosarcoma." (PMID 35321246, 2022). "Comparative genomics of spontaneous human and dog osteosarcomas (OS) expose Disks Large Homolog 2 (DLG2) as a tumor suppressor candidate." (PMID 30093633, 2019). "DLG2 plays a role in pain signaling, and deletion is seen in both human and canine osteosarcoma." (PMID 35982973, 2022). "While the role of DLG2 as a tumor suppressor gene in osteosarcoma and miRNA target in ovarian cancer inhibiting cell migration were reported, its involvement in bladder cancer remains unclear." (PMID 31805718, 2019).
Intellectual disability (8 papers, 2017 to 2024). "It expands the DLG2 NDD phenotypic spectrum to intellectual disability (GDD/ID, language delay) and behavioral disorders (ASD, ADHD)." (PMID 28724449, 2017). "Two pediatric patients with global developmental delay and intellectual disability phenotype underwent array-CGH genetic testing, both showing a partial deletion of the DLG2 gene." (PMID 28724449, 2017).
Anxiety (7 papers, 2012 to 2023). Intense feelings of nervousness, tension, or panic often arise in response to interpersonal stresses. "These included tests of anxiety, social behaviour, and anhedonia, key behavioural domains disrupted across disorders Dlg2 is implicated in." (PMID 35075790, 2022). "In this study, we aimed to investigate the effect of ATRA on the expression of two synaptic- associated genes, DLG2 and SynDIG1, in the hippocampus and their relationship with anxiety- or depression-like behavior in young mice." (PMID 32290523, 2020). "We performed correlation analysis, to explore the association of DLG2 and SynDIG1 expression with anxiety- and depression-like behavior in mice." (PMID 32290523, 2020). "In this study we investigated motor co‐ordination and motor learning, habituation to a novel context, PPI of the acoustic startle response (ASR) and anxiety in heterozygous Dlg2 adult male mice." (PMID 35118804, 2022). "Behaviourally Dlg2+/− rats performed comparably to wild‐types on tests of anxiety, hedonic reactions, social behaviour, and sensorimotor gating." (PMID 35075790, 2022). "Other functions including sensorimotor gating of an acoustic stimulus measured by PPI, motor co‐ordination and anxiety were unaffected in this Dlg2+/− mouse model." (PMID 35118804, 2022). "In agreement with our results, Dlg2 was upregulated in low anxiety, High Activity mice." (PMID 36514243, 2023). "Collectively, given that such behavioral measures of anxiety in rodents greatly depend on the locomotion of a subject, these results with normal locomotion in the home-cage setting suggest that Dlg2–/– mice exhibit context-dependent aberrant locomotor responses to novelty." (PMID 32164788, 2020). "Given that Dlg2-knockout mice in the present study displayed context-dependent abnormalities in locomotion and anxiety-like behaviors, differences in the extent of strangers’ novelty and light intensity during tests might lead to discrepant results." (PMID 32164788, 2020). "Furthermore, Dlg2–/– mice showed a significantly decreased duration of exploring in the light chamber of the light/dark box test, a behavioral test commonly used to measure the level of anxiety in rodents." (PMID 32164788, 2020). "Thus, the specific role of DLG2 in the pathogenesis of anxiety warrants further examination." (PMID 32290523, 2020). "Dlg2 mRNA levels were positively correlated with center duration and total distance traveled in OFA, suggesting lower anxiety‐like behaviors." (PMID 36514243, 2023). "We have recently reported that Dlg2+/− heterozygous rats exhibit an enhanced locomotor response to phencyclidine but are indistinguishable from wild‐types in tests of anxiety, hedonic reactions, social behaviour, and sensorimotor gating." (PMID 37705179, 2023). "In this study of heterozygous Dlg2 male mice we show impaired motor learning and long‐term habituation to a novel context, but normal motor co‐ordination, normal PPI (despite a reduction in acoustic startle response), and normal anxiety state." (PMID 35118804, 2022). "The heterozygous Dlg2 mice exhibited behavioural impairments in long‐term motor learning and long‐term habituation to a novel context, but not motor co‐ordination, initial responses to a novel context, PPI of acoustic startle or anxiety." (PMID 35118804, 2022). "The observed lack of anxiety and pre‐pulse inhibition phenotypes in the Dlg2+/− rat were also found in Dlg2+/− mice." (PMID 35075790, 2022). "There was also an absence of gross behavioural deficits related to anxiety, hedonic reactions, social behaviour, and sensorimotor gating in the model; however, Dlg2+/− rats demonstrated a potentiated hyperlocomotion phenotype in response to PCP administration compared to wild‐types." (PMID 35075790, 2022).
Anxiety (continued). "Dlg2+/− and wild‐type rats placed in the EPM or open field for 5 and 10 min, respectively, would not have habituated to the apparatus, as is crucial for anxiety tests, meaning that increased self‐grooming may only be seen after the habituation period." (PMID 35075790, 2022).
colorectal cancer (6 papers, 2015 to 2025). A primary or metastatic malignant neoplasm that affects the colon or rectum. "Recently, FAT atypical cadherin 3 (FAT3), kinectin 1 (KTN1), discs large homolog 2 (DLG2) and deleted in colorectal cancer (DCC) have been reported to be associated with the function of the human mesolimbic reward system, which is the neurobiological basis of drug addiction." (PMID 27676367, 2016). "For example, DLG2 inhibited colorectal cancer tumor property through the circ0106714/miR-942-5p/DLG2 pathway." (PMID 39856747, 2025). "Previous studies suggested that as a tumor suppressor gene, DLG2 functioned by inhibiting stemness and promoting apoptosis in OC 27, and DLG2 suppressed colorectal cancer via enhancing phosphorylation of Yap1 in colorectal cancer." (PMID 37416779, 2023). "A large downregulation in DLG2 was seen in the paired healthy-tumor colon tissue from colorectal cancer patients (log2 FC = 12.6, p < 0.001)." (PMID 35499706, 2022). "The malignant phenotypes of colorectal cancer cells were enhanced by miR-942-5p via targeting DLG2." (PMID 35111846, 2022). "Using the dataset (GSE24551) to determine the if the expression of DLG2 resulted in altered survivability in colorectal cancer patients we performed a Kaplan–Meier survival analysis, with high DLG2 expression increasing the probability of 5-year patient survival." (PMID 35499706, 2022). "The stimulation of DLG2 expression by circ0106714 could promote Yap phosphorylation, thereby suppressing the progression of colorectal cancer (CRC)." (PMID 35111846, 2022). "The expression of DLG2 is repressed in inflammatory colon diseases IBD and Ulcerative colitis as well as colorectal cancer tissue compared to healthy individuals." (PMID 35499706, 2022). "The heatmap of individual samples, revealed a trend of high Bcl6, low Dlg2 and high MAPK9 in many colorectal carcinoma samples relative to the normal intestinal mucosa." (PMID 26187947, 2015).
epilepsy (5 papers, 2017 to 2022). A brain disorder characterized by episodes of abnormally increased neuronal discharge resulting in transient episodes of sensory or motor neurological dysfunction, or psychic dysfunction. "Also, while patients in the DLG2 cohort have cognitive, behavioral, or psychiatric disorders, remarkably only one out of 29 has an epilepsy phenotype, suggesting this neurodevelopmental phenotype is less often associated with DLG2 deletion." (PMID 28724449, 2017). "The direct interaction between the DLG2 and Kirchannels determining the functional maturation of spiny projection neurons during a critical period of striatal circuit development may concur with the strong association between epilepsy and ASD." (PMID 35627244, 2022). "DLG2 belongs to the gene motif “BGNADP”, which is a network associated with ID and epilepsy, including also BTD, GALNT10, NMUR2, AUTS2, and PTPRD." (PMID 35627244, 2022). "Identically, DLG2 has never been linked to epilepsy except for anecdotal reports." (PMID 28724449, 2017).
Alzheimer disease (4 papers, 2011 to 2024). A progressive, neurodegenerative disease characterized by loss of function and death of nerve cells in several areas of the brain leading to loss of cognitive function such as memory and language. "In the Alzheimer’s Disease Dataset analysis (GSE48350) from the GEO database expression of DLG2 and DTNB is significantly decreased in AD compared to control subjects in at least one of two microarray ids corresponding to the genes." (PMID 35246634, 2022). "Furthermore, a recent study employing longitudinal imaging combined with genetic analyses has demonstrated that single nucleotide polymorphisms (SNPs) in DLG2/PSD-93 are associated with structural asymmetry of subcortical regions, including putamen in patients with Alzheimer’s disease (AD)." (PMID 35966008, 2022).
depression (4 papers, 2015 to 2024). "It has been reported that a reduction of DLG2 expression is found in the hippocampus in depression disorders, and DLG2 might be involved in depression disorders, according to results of a genome-wide association study." (PMID 32290523, 2020). "Furthermore, the reduction of DLG2 mRNA expression in the hippocampus has been found in depression disorders, which is consistent with our results in an ATRA-induced model of depression." (PMID 32290523, 2020).
glioma (4 papers, 2021 to 2026). A benign or malignant brain and spinal cord tumor that arises from glial cells (astrocytes, oligodendrocytes, ependymal cells). "It was found by humanbase tool that DLG2 was lowly expressed in patients at the initial stage of glioma, which was associated with poor prognosis." (PMID 35111846, 2022). "Finally, DLG2 was further downregulated in glioma cells to detect the association between AKIP1 and DLG2 in the cellular functions of glioma." (PMID 35111846, 2022). "DLG2 inhibited the epithelial-mesenchymal transition of glioma cells by regulating the AKIP1/DLG2 pathway." (PMID 39856747, 2025). "To substantiate the prediction that DLG2 expression was decreased in glioma cells from CCLE website, we measured its levels in HEB and T98G cells." (PMID 35111846, 2022). "To conclude, this study presents evidence that AKIP1 silencing suppresses the progression of glioma via targeting DLG2." (PMID 35111846, 2022). "Then, we tested if AKIP1 exerted effects on the T98G cell functions to affect the progression of glioma by regulating DLG2." (PMID 35111846, 2022). "Medulloblastoma (6/7), Ewings sarcoma (2/2), glioma (6/7), pheochromocytomas/paragangliomas (2/2) and NB (5/5) all showed high DLG2 expression as well as high LIN7A expression." (PMID 33726762, 2021). "The results of CCLE website also showed that the expression of DLG2 was downregulated in glioma." (PMID 35111846, 2022). "Humanbase demonstrated the interplay between AKIP1 and DLG2, and we further employed CGGA database to discover that AKIP1 was in negative association with DLG2 in primary and recurrent glioma." (PMID 35111846, 2022). "Notably, the inhibitory impacts of AKIP1 insufficiency on the proliferation, migration, invasion, and EMT process of T98G cells were reversed by silencing of DLG2, which indicated that AKIP1 modulated these cell functions so as to affect glioma development by targeting DLG2." (PMID 35111846, 2022). "In addition, CGGA database indicated the negative correlation between the expression of AKIP1 and DLG2 in primary and recurrent glioma." (PMID 35111846, 2022). "DLG2, which was lowly expressed in glioma cells, demonstrated a negative link to AKIP2." (PMID 35111846, 2022).
breast carcinoma (3 papers, 2021 to 2024). "The remainder of the tumor dataset, consisting of lung-, colon-, ovarian-, and breast cancers and various lymphomas tended to show low expression of both DLG2 and LIN7A." (PMID 33726762, 2021).
cervical carcinoma (3 papers, 2020 to 2025). A carcinoma arising from either the exocervical squamous epithelium or the endocervical glandular epithelium. "Discs large homolog 2 (DLG2) has been implicated in cancer development, yet its role in cervical cancer remains unclear." (PMID 39856747, 2025). "Another paper revealed that DLG2 could be implicated in the carcinogenesis of cervical cancer caused by HPV." (PMID 39856747, 2025). "Thus, we postulated that the METTL3/DLG2/Hippo signaling pathway was implicated in the progression of cervical cancer, and this hypothesis has been substantiated in the current work." (PMID 39856747, 2025). "In particular, the combination of METTL3 inhibitors or DLG2 activators with current cervical cancer therapies has the potential to improve treatment outcomes by leveraging a more comprehensive and targeted approach against the disease." (PMID 39856747, 2025). "This study aims to explore the regulatory mechanism of DLG2 in cervical cancer and its clinical implications." (PMID 39856747, 2025). "We analyzed DLG2 expression in cervical cancer tissues and normal cervical tissues through the online databases including GEPIA and UALCAN." (PMID 39856747, 2025). "Elevating DLG2 levels significantly suppressed cervical cancer cell proliferation, migration, and invasion, while promoting apoptosis." (PMID 39856747, 2025). "We found a lower DLG2 expression in cervical cancer tissues through the online databases including GEPIA and UALCAN." (PMID 39856747, 2025). "We then analyzed the effects of DLG2 on the malignant phenotypes of cervical cancer cells, including cell proliferation, apoptosis, migration, and invasion." (PMID 39856747, 2025). "The analysis of clinical tissue samples showed that DLG2 expression at mRNA and protein levels was lower in cervical cancer tissues than in normal cervical tissues." (PMID 39856747, 2025). "Three genes of LRP1B, FHIT, and DLG2 belong to a group of 9 genes that have been reported to be the most frequently integrated spots for HPV in cervical carcinomas." (PMID 32905102, 2020). "We further analyzed whether DLG2 was involved in the regulation of METTL3 in the malignant phenotypes of cervical cancer cells." (PMID 39856747, 2025). "In addition, DLG2 overexpression inhibited cervical cancer cell proliferation, migration, and invasion and induced cell apoptosis." (PMID 39856747, 2025). "The METTL3-dependent regulation of DLG2 mRNA stability could be a critical factor in cervical cancer progression." (PMID 39856747, 2025). "Thus, DLG2 inhibited cervical cancer cell proliferation, migration, and invasion and promoted cell apoptosis." (PMID 39856747, 2025). "DLG2 acted as a tumor suppressor in cervical cancer by inhibiting the Hippo/YAP signaling pathway." (PMID 39856747, 2025). "DLG2 was underexpressed in cervical cancer tissues and cells." (PMID 39856747, 2025). "Moreover, lowering DLG2 expression mitigated the effects of METTL3 silencing on cervical cancer cell malignancy." (PMID 39856747, 2025). "Moreover, DLG2 silencing attenuated METTL3 knockdown-induced effects in cervical cancer cells, indicating that the METTL3/DLG2 axis was involved in cervical cancer progression." (PMID 39856747, 2025). "Notably, LRP1B and DLG2 are also integration hot spot genes in cervical cancer identified by long read sequencing." (PMID 38279874, 2024). "Thus, DARS-AS1 might be required for the modulation of METTL3 in the DLG2/Hippo/YAP signaling in cervical cancer progression." (PMID 39856747, 2025). "Thus, METTL3 might promote the malignant progression of cervical cancer cells by decreasing DLG2 expression." (PMID 39856747, 2025). "Thus, DLG2 could inactivate the Hippo/YAP signaling in cervical cancer cells." (PMID 39856747, 2025). "Thus, DLG2 might inhibit the malignant growth of cervical cancer cells in vivo." (PMID 39856747, 2025).
cervical carcinoma (continued). "We identified a novel mechanism by which METTL3 destabilized DLG2 expression to activate the Hippo/YAP pathway, thus promoting cervical cancer progression." (PMID 39856747, 2025). "Taken together, cervical cancer progression involved a high METTL3 expression, and the elevated METTL3 expression reduced DLG2 release in an m6A-dependent manner to activate the Hippo/YAP pathway, further promoting tumor cell proliferation, migration and invasion and inhibiting cell apoptosis." (PMID 39856747, 2025).
Ewing sarcoma (3 papers, 2009 to 2025). A small round cell tumor that lacks morphologic, immunohistochemical, and electron microscopic evidence of neuroectodermal differentiation. "Ewing’s sarcoma (2/2) and NB (5/5) clustered with high DLG2 expression as well as high LIN7B expression." (PMID 33726762, 2021). "Ewings sarcoma (2/2) and NB (5/5) clustered with high DLG2 expression as well as high LIN7C expression." (PMID 33726762, 2021).
ovarian carcinoma (3 papers, 2019 to 2022). A malignant neoplasm originating from the surface ovarian epithelium. "DLG2 was lowly expressed in ovarian cancer (OC), and the inhibition of microRNA-23a inhibited OC cell viability, invasion, and migration by releasing DLG2." (PMID 35111846, 2022).
psychosis (3 papers, 2022 to 2023). "Together with our data, this suggests disruptions that AMPAR‐mediated signalling involving DLG2 at glutamatergic synapses is a mechanism underlying behavioural habituation deficits that are core for psychosis." (PMID 35118804, 2022). "Behaviourally Dlg2+/− rats show a potentiated locomotor response to phencyclidine, as is typical of psychotic disorder models, in the absence of deficits in the other behavioural phenotypes assessed here." (PMID 35075790, 2022).
asthma (2 papers, 2018 to 2025). "Interestingly, in a recent genome wide analysis for gene-environment interaction effects on childhood asthma differential methylation and expression of DLG2 was found associated with air pollution exposure." (PMID 29703139, 2018). "A genome‐wide interaction analysis of air pollution exposure and childhood asthma showed interactions with three genes, ADCY2, B4GALT5, and DLG2, which have been found to be important for the development of asthma." (PMID 40133993, 2025).
mental disorder (2 papers, 2018 to 2025). A disease that has its basis in the disruption of mental process. "Dysfunction of the Dlg family has been implicated in several mental disorders: Dlg4 (also known as PSD95 or SAP90), Dlg1 (also known as SAP97), and Dlg2 (also known as PSD93 or Chapsin110)." (PMID 40360818, 2025).
renal cell carcinoma (2 papers, 2006 to 2019). "Copy number losses were also identified in DLG2 (8% WGS samples), SETD2 (4% WGS), and DMD (29% WGS), genes previously associated with other human cancers such as OS, renal cell carcinoma and myogenic sarcomas." (PMID 31341965, 2019). "On the other hand, the results of RT-PCR indicate the expression of the known isoform of DLG2 in all other types of renal cell cancer whereas RO shows a low expression level." (PMID 16640776, 2006).